KMO (kynurenine 3-monooxygenase)
Diseases named in the same sentence as KMO in open-access papers (continued):
Sharing a sentence is not in itself a finding about the gene and the disease.
Cerebral ischemia (2 papers, 2011 to 2024). Restriction of arterial blood supply to the brain associated with insufficient oxygenation to support the metabolic requirements of the tissue. "Our study thus provides a proof-of-concept that circSCMH1 can function as a novel inhibitor of KMO and thus has the potential to be a therapeutic target for efforts to manage metabolic disorders after cerebral ischemia." (PMID 39659575, 2024). "It is now appreciated that cerebral 3-hydroxykynurenine and quinolinic acid concentrations can be manipulated, selectively without altering KYNA concentrations, by inhibition of KMO, an approach which shows neuroprotective effects in animal models of cerebral ischemia." (PMID 21324164, 2011).
cognitive deficits (2 papers, 2023 to 2025). "In these models, KMO inhibition-induced KYNA elevation was consistently associated with cognitive deficits." (PMID 41020827, 2025). "KYN is converted to kynurenine acid by KAT (kynurenine aminotransferase) in astrocytes, which can cause cognitive deficits, and is transformed to quinolinic acid by KMO (kynurenine 3-monooxygenase) in microglia, which causes neurotoxicity, including oxidative stress and neurodegeneration." (PMID 37396924, 2023). "The present study confirmed the significant antiepileptic and anti-depressant effects of the KMO inhibitor Ro 61-8048 in an epileptic mouse model, without aggravating cognitive impairment." (PMID 41020827, 2025). "The results confirmed that KMO inhibition exerts significant dual therapeutic effects: it effectively alleviates seizure severity and improves depressive-like behaviors, without exacerbating cognitive impairment—conversely, it confers a certain improvement in cognitive performance." (PMID 41020827, 2025).
epilepsy (2 papers, 2022 to 2025). A brain disorder characterized by episodes of abnormally increased neuronal discharge resulting in transient episodes of sensory or motor neurological dysfunction, or psychic dysfunction. "In this study, we employed a murine epilepsy model treated with the KMO inhibitor Ro 61-8048, a selective inhibitor extensively validated preclinically that specifically binds and inhibits KMO enzymatic activity." (PMID 41020827, 2025). "Future studies will further explore the long-term efficacy and safety of KMO inhibitors across various epilepsy models and delve into their multi-targeted mechanisms of action on neurotransmitter systems and neuroinflammation, laying the foundation for clinical applications." (PMID 41020827, 2025).
glioblastoma (2 papers, 2021). The most malignant astrocytic tumor (WHO grade IV). "Nevertheless, the biological function of KMO in immunomodulation in glioblastoma and other cancers, as well as the association between KMO expression and the GBM genomic profile, should be clarified." (PMID 34440798, 2021). "In this context, our group recently found a kynurenine monooxygenase (KMO) expression and activity in human glioblastoma cell culture as well as in the GBM patient's samples." (PMID 34557553, 2021).
invasive breast carcinoma (2 papers, 2021 to 2023). A carcinoma that infiltrates the breast parenchyma. "In the context of TNBC, elevated tumoral KMO is associated with worse overall survival and invasive breast cancers have among the highest rates of KMO copy number amplification." (PMID 37876966, 2023). "The results indicated that the mRNA expression of KMO was significantly higher in invasive ductal breast carcinoma, invasive lobular breast carcinoma, lobular breast carcinoma, invasive breast carcinoma, and ductal breast carcinoma in situ compared with matched normal tissues." (PMID 34683090, 2021).
ischemia (2 papers, 2018 to 2025). A hypoperfusion of the BLOOD through an organ or tissue caused by a PATHOLOGIC CONSTRICTION or obstruction of its BLOOD VESSELS, or an absence of BLOOD CIRCULATION. "Presently, enzyme‐based therapies are in development, and Ro‐61‐8048 (the most extensively used KMO inhibitor) has shown neuroprotective efficacy in focal or global ischemia." (PMID 40260682, 2025).
liver cancer (2 papers, 2025). An epithelial or non-epithelial malignant neoplasm that arises from the liver. "Experimental studies have demonstrated that reduced KMO expression promotes proliferation, invasion, and metastasis while inhibiting apoptosis in liver cancer cells, partly through its involvement in the epithelial-mesenchymal transition (EMT) process." (PMID 40391162, 2025). "In the present study, leveraging GEO liver cancer-related expression data, we identified 42 genes that are commonly downregulated in HCC tissues compared to normal tissues, with COLEC10, KMO, and GNMT being the most frequently altered." (PMID 40026364, 2025).
myocardial ischemia (2 papers, 2023 to 2025). A disorder of cardiac function caused by insufficient blood flow to the muscle tissue of the heart. "Given the critical role of KMO in myocardial ischemia injury, potential KMO inhibitors were further screened by molecular docking and SPR techniques." (PMID 37416768, 2023). "Above results indicated that KMO inhibition was essential in the protection of myocardial ischemia injury by maintaining mitochondrial fusion and fission balance." (PMID 37416768, 2023). "This study firstly demonstrated that KMO inhibition effectively ameliorated myocardial ischemia injury." (PMID 37416768, 2023). "Besides, ginsenoside Rb3 was screened as the novel inhibitor of KMO, and it also exhibited an excellent therapeutic effect on myocardial ischemia by maintaining mitochondrial fusion and fission balance." (PMID 37416768, 2023). "Inhibition of kynurenine 3-monooxygenase (KMO) significantly suppressed XA elevation and attenuated both oxygen-glucose deprivation (OGD)-induced cardiomyocyte injury and ligation-induced myocardial ischemia injury, suggesting XA's potential utility as a ferroptosis marker in CAD." (PMID 40308274, 2025). "Our results demonstrated that inhibition of kynurenine 3-monooxygenase (KMO) profoundly ameliorated myocardial injury by maintaining mitochondrial fusion and fission balance, which may reveal a novel potential therapeutic strategy for myocardial ischemia." (PMID 37416768, 2023).
neuroblastoma (2 papers, 2011 to 2014). Neuroblastoma (NB) is the most common solid, extracranial childhood tumor. "Expression of KYNU and KMO mRNA was shown to be present at low levels in both the IFN-γ stimulated and unstimulated in the SK-N-SH neuroblastoma cell line." (PMID 25415278, 2014).
retinal (2 papers, 2021 to 2023). "Studying this mechanism is an interesting new direction since the data on the role of KMO activation and overproduction of 3OH-K in retinal pathologies are currently very scarce." (PMID 33494373, 2021).
Viral infection (2 papers, 2019 to 2022). "Viral infection upregulated the expression of Kmo as significantly higher Kmo mRNA levels were detected in KMO+/+ animals after EMCV infection." (PMID 31781097, 2019). "Our further analysis demonstrated that IFITM2, KMO, LIPG genes exerted the most obvious inhibition against viral infections in this study." (PMID 35235615, 2022). "As KMO had a novel function against viral infection by enhancing IFN-I induction, we wanted to determine the breadth of antiviral activity of KMO." (PMID 35235615, 2022). "However, the role of KMO in modulating innate immunity against viral infections has not been investigated." (PMID 35235615, 2022). "So far, the role of KMO in innate immunity response to viral infections has not been reported yet." (PMID 35235615, 2022).
aortic aneurysm (1 paper, 2021). A ruptured aneurysm located in the wall of the proximal portion of the descending aorta proceeding from the arch of the aorta. "However, further in vivo experiments using KMO inhibitor or knockout animals will help clarify the effects and potential mechanism of KMO in aortic aneurysms and related aortic diseases." (PMID 34630411, 2021).
atherosclerosis (1 paper, 2024). A disease characterized by the build-up of fatty material and calcium deposition in the arterial wall resulting in partial or complete occlusion of the arterial lumen. "Secondly, further in vivo and in vitro investigations are warranted to elucidate the underlying mechanisms governing the relationship between KMO and immune cell infiltration in atherosclerosis." (PMID 39026250, 2024). "Elevated KMO expression was associated with the promotion of atherosclerosis progression." (PMID 39026250, 2024). "In future, it is crucial to undertake additional research to explore the potential role of KMO in promoting atherosclerosis via mitochondrial dysfunction and elucidate the specific mechanisms underlying its regulation of mitochondrial dysfunction." (PMID 39026250, 2024). "The findings provide strong evidence that KMO participates in atherosclerosis by mediating macrophage function." (PMID 39026250, 2024). "Research in these areas will provide a more comprehensive understanding of the role of KMO in atherosclerosis and its potential therapeutic implications." (PMID 39026250, 2024). "However, additional in vivo and in vitro experiments are necessary to further elucidate the potential molecular mechanisms by which KMO mediates macrophage function in atherosclerosis." (PMID 39026250, 2024). "Additionally, it is essential to explore the potential contribution of KMO to atherosclerosis progression through mitochondrial dysfunction and investigate the specific regulatory pathways involved." (PMID 39026250, 2024).
Autoimmunity (1 paper, 2019). The occurrence of an immune reaction against the organism's own cells or tissues. "With respect to diseases related to disorders of the immune system, such as infectious diseases, chronic inflammation, autoimmunity and cancer, these models have focused on three KP enzymes: IDO, tryptophan 2,3-dioxygenase (TDO) and kynurenine 3-monooxygenase (KMO)." (PMID 31781097, 2019).
brain tumors (1 paper, 2014). "Collectively, our data provide the foundation and rationale for further investigation into determining the potential therapeutic effects of KYNU and KMO pharmacological inhibitors in brain tumors." (PMID 25415278, 2014).
carotid atherosclerosis (1 paper, 2024). A thickening and loss of elasticity of the walls of carotid arteries that occur with formation of atherosclerotic plaques. "The results revealed the co-localization of KMO within CD68-positive macrophages, consistent with the findings derived from our study utilizing WGCNA, machine learning, and immune cell infiltration analysis on a publicly available dataset of human carotid atherosclerosis." (PMID 39026250, 2024).
cataract (1 paper, 2025). Partial or complete opacity of the crystalline lens of one or both eyes that decreases visual acuity and eventually results in blindness. "Despite growing interest in KP metabolites as biomarkers, no study has yet mapped KAT and KMO activities across SPONCS grades to elucidate how flux through each branch relates to cataract severity." (PMID 40648903, 2025). "In contrast, neither KMO activity nor the 3-HK/KYNA ratio differed among the cataract groups." (PMID 40648903, 2025).
cerebral malaria (1 paper, 2017). A sequestration of Plasmodium falciparum in the brain, which can cause coma and/or seizures. "Similarly, in a murine form of cerebral malaria, KMO inhibition prevented the death of the infected mice, prolonging the normal 7-day survival period to at least 21 days." (PMID 28013248, 2017).
cocaine use disorder (1 paper, 2024). A substance-related disorder that involves the recurring use of cocaine despite negative consequences. "One example is Ro 61-8048, a KMO inhibitor, which has shown promising results as a therapeutic option to help prevent relapse in cannabis and cocaine use disorder." (PMID 39596587, 2024).
dementia (1 paper, 2014). Loss of intellectual abilities interfering with an individual's social and occupational functions. "Since NF-κB also stimulates IDO, KMO, and KYNU, it is possible that proinflammatory cytokine signaling underlies a vicious cycle that promotes viral replication, tryptophan/kynurenine metabolism, and progression of dementia symptoms." (PMID 24567701, 2014).
encephalitis (1 paper, 2018). An acute inflammatory process affecting the brain parenchyma. "In our study, the ratio of the neuroprotective metabolite KYNA to the sum of neurotoxic metabolites 3-HK and QA was lower for patients with encephalitis compared to the other groups, which could indicate a stronger activation of the KMO branch in encephalitis." (PMID 30470234, 2018).
injury (1 paper, 2020). Damage inflicted on the body as the direct or indirect result of an external force, with or without disruption of structural continuity. "It has been found that traumatic brain injury activates the KP resulting in elevated QUIN, and another study showed that KMO plays an important role in RGC death in mice subjected to traumatic brain injury." (PMID 32151061, 2020).
invasive ductal breast carcinoma (1 paper, 2021). The most common type of invasive breast carcinoma, accounting for approximately 70% of breast carcinomas. "In this study, we found that KMO was highly expressed in different types of tumors, especially in invasive ductal breast carcinoma." (PMID 34683090, 2021).
liver cirrhosis (1 paper, 2015). "Our data showed that KMO expression exhibited a progressiveincrease from liver cirrhosis to HCC (p < 0.05)." (PMID 26099564, 2015). "Inaddition, our data also showed a progressive increase of KMO from liver cirrhosis toHCC." (PMID 26099564, 2015).
malaria (1 paper, 2020). Malaria is a serious and sometimes fatal disease caused by a parasite that commonly infects a certain type of mosquito which feeds on humans. "Also, the study highlighted the important effects of xanthurenic acid on the development of Plasmodium in Anopheles mosquito and suggested that KMO is a possible target for blocking malaria transmission." (PMID 32912275, 2020).
metabolic syndrome (1 paper, 2020). A cluster of metabolic risk factors for CARDIOVASCULAR DISEASES and TYPE 2 DIABETES MELLITUS. "It has been reported that a peripheral KMO deficiency leads to metabolic syndrome in schizophrenic patients." (PMID 32151061, 2020).
multiple myeloma (1 paper, 2023). "Metabolism of kynurenine by kynurenine-3-monooxygenase (KMO) led to dysfunction of pDCs and immunosuppressive activity in multiple myeloma." (PMID 37277776, 2023).
neuropathy (1 paper, 2018). A disorder affecting the nervous system that manifests with pain, tingling, numbness, and/or muscle weakness. "The results of our studies show that the kynurenine pathway is an important mediator of neuropathic pain pathology in rats and indicate that IDO2 and KMO represent novel pharmacological targets for treating neuropathy." (PMID 30050435, 2018). "The results of our studies show that the IDO2 and KMO enzymes of the kynurenine pathway are important for the development of neuropathic pain and indicate that they represent a novel pharmacological target for the treatment of neuropathy." (PMID 30050435, 2018). "Our data once again suggest KMO as an important target for neuropathy treatment." (PMID 30050435, 2018).
nicotine dependence (1 paper, 2018). Physical and psychological dependence on nicotine. "Even though a recent study showed that kynurenine 3-monooxygenase inhibition by Ro 61-8048 is promising for the treatment of nicotine addiction, there could also be genomic approaches for this problem." (PMID 29951083, 2018).
ocular hypertension (1 paper, 2025). Abnormally high intraocular pressure. "Similarly, although small-molecule KMO inhibitors (such as CHDI-340246) have shown promise in Huntington’s models, their ocular bioavailability, safety profile, and efficacy in rodent models of ocular hypertension remain untested." (PMID 40648903, 2025).
pancreatitis (1 paper, 2020). Inflammation of the pancreas. "However, human pancreatitis is highly heterogeneous, so further studies are necessary to demonstrate whether KMO inhibitors are suitable for all pancreatitis." (PMID 32148781, 2020).
peripheral nerve injury (1 paper, 2022). Injury to a peripheral nerve. "In this study, we used a considerable number of different approaches to show that in the spinal cord, KMO is mainly expressed and upregulated in astrocytes after peripheral nerve injury." (PMID 36227694, 2022). "Collectively, these results indicate that, after peripheral nerve injury, astrocytes expressing KMO mediate neuropathic pain development probably through conversion of Kyn into downstream pronociceptive factors, such as 3-Hk." (PMID 36227694, 2022).
postpartum depression (1 paper, 2021). A type of clinical depression that occurs after childbirth. "In Asian women suffering from postpartum depression (PPD), the polymorphisms of KMO SNP rs1053230 AG genotype had higher 3-HK/kyn ratio indicative of increased KMO activity and associated with PPD." (PMID 34205235, 2021).
Proteinuria (1 paper, 2025). Increased levels of protein in the urine. "Proteinuria has been reported in mice lacking the KP enzyme kynurenine-3-monooxygenase (KMO), although an alternative study of KMO knockout mice reported normal renal function under physiological conditions." (PMID 41343438, 2025).
small cell lung carcinoma (1 paper, 2021). Small cell lung cancer (SCLC) is a highly aggressive malignant neoplasm, accounting for 10-15% of lung cancer cases, characterized byrapid growth, and early metastasis. "Knockdown of CCT5, PIP4K2A, EXO1, CMBL, OPN3, and KMO, genes within 200 kb up/downstream of the three SNPs that were corresponded with small cell lung cancer (SCLC) overall survival." (PMID 33869000, 2021).
substance abuse (1 paper, 2024). The use of a drug for a reason other than which it was intended or in a manner or in quantities other than directed. "Therefore, this present study is carried out to investigate the association of genetic polymorphisms of IDO1/2, TDO2, and KMO as biomarkers for increased risk of substance abuse in the AoU database." (PMID 39596587, 2024).
temporal lobe epilepsy (1 paper, 2014). A localization-related (focal) form of epilepsy characterized by recurrent seizures that arise from foci within the temporal lobe, most commonly from its mesial aspect. "Consistent with the induction of microglial IDO and KMO by proinflammatory cytokine signaling in a mouse model of temporal lobe epilepsy, hippocampal elevations in mRNA encoding IL-1β, TNF-α, IFN-γ, CD11b, IDO, and KMO were detected 24 h after kainic acid injection." (PMID 24567701, 2014).